ALKBH5 (alkB homolog 5, RNA demethylase)
Diseases named in the same sentence as ALKBH5 in open-access papers (continued):
Sharing a sentence is not in itself a finding about the gene and the disease.
inflammation (1 paper, 2024). Aberrant reaction of the microcirculation characterized by movement of fluid and leukocytes from the blood into extravascular tissues. "To further confirm the expression of METTL14, WTAP, METTL3, FTO and ALKBH5 in NPC tissues, we utilized RT‐qPCR to detect their expression in 28 NPC tissues and 7 nasopharyngeal chronic inflammation tissues." (PMID 39021049, 2024).
neurological diseases (1 paper, 2025). "Research has shown that ALKBH5 expression undergoes significant changes in the biological processes of various neurological diseases." (PMID 40001461, 2025). "This review provides an overview of the structural and functional characteristics of ALKBH5 and the involvement of ALKBH5 in diverse human diseases, including metabolic, immune, reproductive, and nervous system disorders, as well as the development of inhibitors." (PMID 40001461, 2025).
ALKBH5 also shares sentences with these, for which no sentence is quoted: hypopharyngeal squamous cell carcinoma (3 papers); alopecia (2); Alzheimer disease (2); breast invasive carcinoma (2); Cerebral ischemia (2); diffuse large B-cell lymphoma (2); heart failure (2); infarction (2); intervertebral disc degeneration (2); Myocardial fibrosis (2); primary Sjögren’s syndrome (2); type II diabetes (2); uterine corpus endometrial carcinoma (2); acute liver failure (1); acute lung injury (1); acute promyelocytic leukemia (1); adenomyosis (1); adrenocortical carcinoma (1); age-related macular degeneration (1); Allergy (1); ankylosing spondylitis (1); asthenozoospermia (1); autoimmune thyroid disease (1); basal cell carcinoma (1); bladder tumors (1); bladder urothelial carcinomas (1); blood disease (1); bone metastasis (1); Burkitt lymphoma (1); cerebral infarction (1).
A further 51 diseases each share a sentence with ALKBH5 in 1 paper.